EGF (epidermal growth factor)
Diseases named in the same sentence as EGF in open-access papers (continued):
Sharing a sentence is not in itself a finding about the gene and the disease.
cancer (continued). "However, the effect of gefitinib on suppressing CLDND1 expression in various types of cancer cells and the kinase signaling pathway downstream of EGF signaling is yet to be elucidated, and thus is a subject for future studies." (PMID 35892692, 2022). "Two important improvements over earlier reports are (i) our SW620 observations relate to a human carcinoma line, enabling insights to the EGF pathway in cancer directly and (ii) we have spatial information concerning EGFR and EGF localization simultaneously from labelled protein and ligand." (PMID 35612280, 2022). "Interestingly, ROS plays a critical role in the proliferation of cancer cells induced by EGF and VEGF by activating MAPK and PKC pathways." (PMID 35799889, 2022). "Protein phosphatase 2 regulatory subunit B alpha (PPP2R3A) regulates several important signal transduction pathways related to cancer including the Wnt signaling cascade, adenosine monophosphate‐activated protein kinase activity, and epidermal growth factor (EGF)/EGF receptor signaling pathway." (PMID 35128835, 2022). "EGFR sialylation affected EGF-mediated cancer cell proliferation." (PMID 33827580, 2021). "Next, EGF was used to further probe the role of EGFR/ERK pathway in UC2288 anti-cancer ability." (PMID 33442398, 2021). "These cells are able to undergo the EGF-induced malignant transformation and consequently to form anchorage-independent colonies in soft agar; therefore, this well-established model is widely used for identification of cancer-preventive agents." (PMID 34677457, 2021). "In addition, it is also noteworthy that sorafenib is known to affect key biological processes in cancer progression as, for example, cell viability, motility or invasion, which are also triggered by EGF signalling (for a review see Ref." (PMID 34655447, 2021). "The role of chemoattractants (e.g., EGF) and surface receptors (e.g., EphA2) as driving molecules controlling cell adhesion and migration in cancer has been a focus of study for many years, and has been exploited for targeting of drug delivery and cancer treatment." (PMID 35096972, 2021). "In addition, MDSCs induce epithelial to mesenchymal transition (EMT) of cancer cells through signaling pathways such as TGF-β and EGF, which is conducive to the spread of cancer cells." (PMID 33986252, 2021). "By treating SKOV3 and 59M cells with EGF over a 6-day period, we noted a dramatic change in morphology compared to controls (untreated and acetic acid treated cancer cells), with cells losing their rounded, cobblestone appearance to become elongated with marginal cell-cell contacts." (PMID 34592589, 2021). "Furthermore, TAMs were found to significantly increase the migration and invasion of cancer cells via overexpression of epidermal growth factor." (PMID 34174813, 2021). "In CRC patients, the binding of VEGF/VEGFR results in migration, invasion, and survival of cancer cells, while the binding of EGF/EGFR results in cell proliferation, vascular permeability, and cancer cell survival, all leading to angiogenesis which is one of the main derivers of CRC." (PMID 33440689, 2021). "Thus, the EGF/EGFR signaling pathway is recognized as an important molecular target in cancer therapy." (PMID 32901097, 2021). "Due to the frequent activation of the PI3K/AKT pathway in HPV positive cancers, we evaluated whether EGF stimulation of this pathway contributed to E7 oncoprotein expression in cells maintaining episomal HPV genomes." (PMID 33481911, 2021). "EGF initiates cancer cell invasion by regulating mitochondrial functions." (PMID 33498743, 2021). "Epidermal growth factor is overexpressed during cancer development, acting as a hepatocyte mitogen." (PMID 34572344, 2021). "EGF-induced nuclear localization of SHC Binding and Spindle Associated 1 (SHCBP1) activates β-catenin signaling by enhancing the CBP/β-catenin interaction and promotes cancer progression." (PMID 33827580, 2021).
cancer (continued). "Cetuximab is an epidermal growth factor (EGFR) inhibitor approved for the treatment of H&N cancers." (PMID 34123780, 2021). "In the organoid library established by Fujii et al26, 22 cancer organoids grew in the absence of exogenous EGF, and in 16 of these EGF‐independent organoids, MAPK signalling pathway mutations were detected." (PMID 34033245, 2021). "Thus, it can serve as a conduit point for IGF-1/epidermal growth factor (EGF) and estrogen signaling in cancer cell adhesion regulation." (PMID 34069554, 2021). "In this work, we developed lysine-free recombinant EGF mutants, where two intrinsic lysine residues were replaced with either serine (S) or arginine (R), to improve anti-cancer effects of EGF-GNPs conjugates by controlling the orientation of EGF against nanoparticle surface." (PMID 34512175, 2021). "Moreover, CBD was found to inhibit the EGF/EGFR pathway in cancer cells, which also inhibits the activation of the pro-inflammatory NF-κB pathway." (PMID 34063802, 2021). "We hypothesize that the optimal combination of CIMAvax-EGF with established therapies can further contribute to transform advanced cancer into a manageable chronic disease, compatible with years of good quality of life." (PMID 34211836, 2021). "EGF/EGFR signaling is recognized as an important molecular target in cancer therapy." (PMID 32901097, 2021). "The media alone significantly increased population of cancer stem cells (CD44+/CD24− phenotype) in TNBCs likely due to the presence of insulin, hydrocortisone and epidermal growth factor that are known to contribute to colony formation characteristic feature of cancer stem cells." (PMID 34873206, 2021). "It has also been shown that TAMs secreted EGF to activate the EGFR/ERK1/2 signal pathway in cancer cells which might promote EMT." (PMID 34965886, 2021). "Epidermal growth factor is the most well-studied growth factor discussed in this review, as it influences many cellular functions, including cell motility and cancer metastasis." (PMID 34093120, 2021). "Moreover, CBD is a potent inhibitor of the EGF/EGFR pathway in cancer cells, which also inhibits the activation of the proinflammatory NFκB pathway." (PMID 33540902, 2021). "Importantly, PI3K activation through EGF has been implicated in invadopodia formation, which are actin-rich basal protrusions that are associated with remodeling of the ECM and cancer metastasis." (PMID 34093120, 2021). "Cancer-associated fibroblasts (CAFs) secrete growth factors, e.g., hepatocyte growth factor (HGF), epidermal growth factor (EGF) and cytokines, e.g., interleukin 6 (IL-6), which activate oncogenic signaling pathways in cancer cells, resulting in chemoresistance." (PMID 33918653, 2021). "Notably, PEVs affect angiogenesis during cancer progression via the overexpression of miR-126, epidermal growth factor (EGF), and platelet-derived growth factor-alpha (PDGFα)." (PMID 34622717, 2021). "The signaling pathways of EGF and TGFβ both represent relevant targets in several cancers." (PMID 33777943, 2021). "We detected significant molecular signals of transcriptional interference with gene expression induced in human cancer cells in response to multiple growth factors such as epidermal growth factor (EGF), insulin-like growth factor-1 (IGF-1), transforming growth factor alpha (TGFA), and many others." (PMID 35155195, 2021). "Thus, the individual EGF blood level can serve as an important biomarker to guide dosage aspects, timing, and overall design of cancer treatment involving EGFR-targeted drugs." (PMID 33748471, 2021). "CDC42 activation is also required for EGF-induced cell migration and protrusion in carcinoma cells." (PMID 33672558, 2021). "Besides CD73 expression was induced by epidermal growth factor (EGF), and the pharmacological inhibition through EGFR-TKi induced its decrease in EGFR-mutated cancer cell lines." (PMID 32760402, 2020).
cancer (continued). "Little is known about the Spns2 regulation in colon cancer, but findings from the studies in other cancer types such as cervix adenocarcinoma underline the importance of Spns2-induced S1P secretion for promotion of cancer cell invasion in response to EGF signaling." (PMID 32456134, 2020). "Introduction of a SAICAR-insensitive or a non-phosphorylatable PKM2 mutant inhibited the EGF-stimulated ERK activation and consequent cancer cell proliferation, suggesting SAICAR-induced PKM2 protein kinase activity is required for EGF-mediated cancer cell proliferation." (PMID 33292198, 2020). "In addition to the canonical activation of EP receptors, PGE2 has been shown to promote cancer progression through the interaction with oncogenic signals, including epidermal growth factor (EGF) and its receptor (EGFR)." (PMID 33271839, 2020). "The effects of rHct-S3 on neoplastic transformation of JB6 Cl41 cells induced by EGF, colony formation and growth of cancer cells were studied by soft agar assay, which is considered to be the most accurate type of in vitro test for detecting malignant transformation of cells." (PMID 33348592, 2020). "All these studies suggest that EGF can regulate PARP1, which might impact the efficacy of cancer therapy, particularly when DNA damage is caused by cancer therapy." (PMID 32093123, 2020). "Besides the EGF pathway, other inflammatory and fibrotic pathways have been identified as valuable cancer targets for prevention." (PMID 33255794, 2020). "Besides ECM proteins, activated and transformed PSCs produce several stimulators such as platelet-derived growth factor (PDGF), connective tissue growth factor (CTGF), and epidermal growth factor (EGF), supporting cancer cell proliferation." (PMID 33333727, 2020). "Epidermal growth factor (EGF) has been shown to induce the migration of various cancer cells." (PMID 32174831, 2020). "Additionally, HDAC6 was responsible for Wnt‐ and EGF‐induced nuclear localization of β‐catenin through deacetylating β‐catenin at different lysine sites in cancer cells." (PMID 32985730, 2020). "Intriguingly, Trpm7 which is transcriptionally increased in the two Memo1 KO mouse models presented here, is needed for EGF-induced cancer cell migration, a function apparently opposite to Memo1’s role in cancer cell motility, where MEMO1 expression is upregulated." (PMID 32706793, 2020). "EGF induces cell migration in the three types of cancer cell used." (PMID 32049991, 2020). "EGF has been shown to induce the migration of various cancer cells." (PMID 32174831, 2020). "On the other hand, it could be speculated that, in cancer cells, autocrine signaling by EGF may potentiate the TRPM6-mediated magnesium influx or compete with CTX." (PMID 33114586, 2020). "In normal cells, SREBP1c is transcribed in response to nutrition and hormonal stimulation whereas in cancer, it is regulated by aberrant growth factor levels such as the epidermal growth factor (EGF), platelet-derived growth factor (PDGF) or excessive steroid hormone signaling." (PMID 32872164, 2020). "Together, these results indicate that EGF mRNA is specifically overexpressed during early carcinogenesis, suggesting that EGF could play a role in this particular stage of cancer." (PMID 32385236, 2020). "The early in vitro studies on miR-31 suggest its role in acquisition of immortality in normal oral keratinocytes, thus progressing into malignant tumors in its early stage, or as a responder when oncogenic processes are initiated by other factors such as epidermal growth factor." (PMID 33007980, 2020).
cancer (continued). "Although accumulating evidences suggested the activation of EGFR contributes to PD-L1 expression in several cancers, it is still unknown whether EGF/EGFR signal was involved in PD-L1 expression in HCC." (PMID 33324209, 2020). "Overall, the activity of TAMs in cancer is usually pro-tumorigenic, closely related to the colony-stimulating factor (CSF)-1 secretion by cancer cells that recruit TAMs, which in turn, by releasing EGF, edit cancer cells and favour cell migration, extravasation and metastases." (PMID 32423420, 2020). "Cell-type selectivity can be achieved by deleting the natural receptor binding capacity of PA63 by single amino acid exchange in its B-domain (mPA63) and fusing peptide ligands for receptors on the surface of certain cancer cells such as EGF or ZHER2, the ligand for HER2 receptor." (PMID 32384736, 2020). "IPA of the 37 plasma-derived sEV protein features with ROC AUCs ≥ 0.70 revealed NKX3-1 (p = 1.4 × 10−9) as a top causal network, Cancer, Cell Death and Survival as a top disease function (p = 1.57 × 10−8) and AHR, VEGF, EGF, IRF1 and STAT3 as predicted significant upstream regulators." (PMID 32370304, 2020). "The EMT process can be triggered by various stimuli, including transforming growth factor-β (TGFβ), epidermal growth factor (EGF), and diverse signaling pathways such as wingless secreted glycoprotein (Wnt)/β-catenin, and have been implicated in cancer regulation." (PMID 33027960, 2020). "EGF/EGFR signal transduction has been known to lead to the constitutive activation of downstream signaling pathways associated with MAPKs, STAT3, and PI3K for regulating PD-L1 expression in various cancer cells." (PMID 32204508, 2020). "As our previous results indicate a significant role for β‐catenin signalling in regulating the anti‐cancer potential of tryptanthrin, A431 cells pretreated with tryptanthrin were exposed to EGF, a known inducer of β‐catenin signalling, for 24 hours and subjected to immunofluorescence analysis." (PMID 31663659, 2020). "HIF-1α interacts with several growth factors and cytokines, such as VEGF, insulin-like growth factors (IGFs), fibroblast growth factors (FGFs), and epidermal growth factor; the expression of these molecules on cancer cells can further enhance cancer cell proliferation and metastasis." (PMID 32793401, 2020). "We further showed that the ablation of ATF6 or inactivation of EGF signaling are promising strategies to break the interplay between dormant cancer cells and their microenvironment, thereby inhibiting the angiogenesis-mediated awakening of dormant cancer cells." (PMID 32630838, 2020). "This increase in stromal cells could be a culprit in treatment resistance, with the proportion of cancer cells to CAFs reaching a state where the secreted EGF levels are sufficient to sustain MAPK signaling in the presence of cetuximab." (PMID 32481658, 2020). "However, when supplemented with increasing concentrations of EGF, cancer cell growth rates increased in proportion with EGF concentration at each cetuximab dose." (PMID 32481658, 2020). "CDC42 is crucial for EGF- stimulated migration in MTLn3 carcinoma cells." (PMID 32733636, 2020). "By contrast, pharmacological dose of flavonoids polyphenols, such as, curcumin, apigenin, EGCG and baicalein, are devoid of PD-L1 modulatory effects when used alone, but suppress the induction of PD-L1 in a variety of cancer cell types treated with either IFN-γ or EGF." (PMID 31783532, 2019). "It indicates that HPV-positive cancer cells are sensitive to extracellular stimulation by EGF." (PMID 31470515, 2019).
cancer (continued). "Interestingly, our results demonstrated that KP markedly reduced EGF-induced Mcl-1 production in HeLa cells, confirming its anti-cancer ability to modulate the EGFR/MAPK signaling cascade." (PMID 31470515, 2019). "The activated EGFR induced by EGF could translocate into the nucleus, and function as a co-transcription factor and kinase to promote proliferation, invasion and survival of cancer cells." (PMID 30971297, 2019). "However, being a major source of MMP-9, EGF, bFGF and TGF-β, MDSCs have been heavily implicated with the EMT promotion and neoangiogenesis in several other types of cancer." (PMID 30927923, 2019). "Also, this is consistent with the literature showing that biochemical cross-talk in NSCLC is driven to a great extent by cancer-derived growth factors, such as EGF and TGF-β1." (PMID 31464606, 2019). "Moreover, this compound exhibited cancer preventive properties, inhibiting epidermal growth factor (EGF)-induced neoplastic transformation in murine cells." (PMID 31181122, 2019). "Therefore, we aimed to evaluate how EGF increases cancer cell invasion during conditions of EGR1 upregulation." (PMID 30845713, 2019). "iEFs inhibit EGFR phosphorylation in EGF-treated cancer cells thereby altering actin cytoskeleton structure and critical processes involved in cell motility—a potential mechanism explaining the observed hindrance of cancer cell motility by iEFs." (PMID 31428691, 2019). "Also, myeloid cells have been shown to induce EMT-like properties in cancer cells via TGFβ, EGF, and HGF." (PMID 31772577, 2019). "Furthermore, Grb7 peptides targeting the SH2 domain of Grb7 impaired the phosphorylation of ERK 1/2 in EGF-stimulated cancers." (PMID 31083325, 2019). "Finally, module 4 included the genes PLCB4, MMP1, CTNNB1, EGF, F2R, and LPAR4, associated with pathways in cancer, Rap1 signalling pathway, and phospholipase D signalling pathways." (PMID 31178673, 2019). "Our and others results together suggest that Cdk5 may be a critical effector to transmit the EGF signaling, leading to reorganization of the actin cytoskeleton and cell migration in cancer cells." (PMID 31548578, 2019). "On the basis of the fact that EGF stimulates cell growth and survival and is a regulator of cancer cell proliferation, we investigated the expression of Ki-67, a marker for cell proliferation that has been used as a potential prognostic or predictive marker in several malignant tumors." (PMID 31470515, 2019). "Epidermal growth factor (EGF) is one of the most important cancer-related genes." (PMID 31053624, 2019). "Additionally, growth hormones such as epidermal growth factor (EGF) increase TIF2/GRIP1 coactivation of androgen receptor activity in recurrent cancer cells." (PMID 31552182, 2019). "Cancer cell migration itself is controlled through a paracrine loop involving colony stimulating factor 1 (CSF1), epidermal growth factor (EGF), and their receptors, which are differentially expressed on carcinoma cells and macrophages, resulting in movement of cancer cells toward macrophages." (PMID 31572718, 2019). "Next, to determine whether the inhibitory effects of AZ304 on cancer cells could be rescued by EGF in long-term proliferation assays, the colony formation assay was implemented." (PMID 29755114, 2018). "According to Igal and co-workers, SCD1 may control cancer cell proliferation via modulation of the epidermal growth factor (EGFR → Akt/ER) signaling pathway." (PMID 29396722, 2018). "However, subsets of cancer cells, including those originating from the breast, respond to epidermal growth factor (EGF) via cell cycle arrest and induction of apoptosis." (PMID 30250119, 2018). "Ginsenoside Rb2 inhibited the migration of cancer cells and was reversed by the treatment of EGF." (PMID 30264477, 2018). "Thus, the cooperation between TGF‐β and EGF/EGFR signaling pathways is likely beneficial to cancer progression." (PMID 29215776, 2018).